TNF (tumor necrosis factor)
Diseases named in the same sentence as TNF in open-access papers (continued):
Sharing a sentence is not in itself a finding about the gene and the disease.
infection (continued). "To measure the ability of GBS or S. suis to induce optimal activation of NK1.1+ cells, we measure surface expression of CD69 and the production of TNF-α, a cytokine described to be produced by these cells in the context of infection." (PMID 28706510, 2017). "Treatment of infected TSLPR−/− mice with anti-IFN-γ mAb systemically reduced IFN-γ and TNF-α levels and rescued the otherwise susceptible TSLPR−/− mice from death due to infection." (PMID 28769924, 2017). "The role of depressed levels of tumor necrosis factor α and granulocyte macrophage colony-stimulating factor in cardiac device pocket infections warrants further investigation." (PMID 28264059, 2017). "During the early phase of infection, i.e., within the first hours, C. burnetii induces a rapid expression of pro-inflammatory cytokines, such as IL-1, IL-12, and TNF-α, in bovine and murine macrophages." (PMID 29379776, 2017). "Taken together, our data demonstrate an essential role for TNF-α and IL-17 in infection-triggered exacerbation of AAI." (PMID 29184554, 2017). "Differential effects of IL-32γ on TNFα, IL-10 and IL-1Ra production after infection with distinct Leishmania species were detected, consistent with the concept that IL-32γ can differently influence the outcome of inflammatory process in leishmaniasis lesions." (PMID 28241012, 2017). "In human VL, there is a strong Th1 cytokine response (IFNγ, IL-1, IL-6, IL-12 and TNFα) at the site of infection, but this is inexplicably unable to control the infection." (PMID 28103263, 2017). "Collectively, our analysis of UL45 and UL48 mutant viruses demonstrate that both UL45 and UL48 are involved in inhibition of TNFα-induced NF-κB activation in the late stages of infection." (PMID 28570668, 2017). "The same additive anti-inflammatory effect of statin was observed in MV rabbits according to TNF-α blood levels as early as the 8th hour following the onset of infection (75% vs. 169% of the baseline value; p<0.001)." (PMID 29149185, 2017). "On the other hand, when the host responds to infection with high levels of pro-inflammatory mediators, such as TNF-α, IFN-γ-inducible protein 10 (IP-10) and monocyte chemotactic protein 1 (MCP-1), the subject also becomes more exposed to plasma leakage events." (PMID 29167501, 2017). "TNF-α is considered one of the earliest proinflammatory cytokines after trauma or infection and helps to propagate the extension of I/R injury." (PMID 28299325, 2017). "To gain a better measure of immunoregulatory balance, we analyzed the TNF-alpha/IL-10 ratio and found that both L. infantum strains induced a lower TNF-alpha/IL-10 ratio in monocytes when compared with infection with L. braziliensis." (PMID 29358935, 2017). "The strain Ab4 induced an increased mRNA expression of IFN-α, IFN-β, and TNF-α after infection of equine respiratory epithelial cells (EREC)." (PMID 28925977, 2017). "Flores reported that mice produced significantly less IL-1β and TNF-α during the early phase of infection." (PMID 28785250, 2017). "Both MAT and CTRL OT-I effector T cells had similar percentages of IFN-γ- and TNF-α-producing cells at the site of the infection (PEC)." (PMID 28337207, 2017). "TNF-α is released by macrophages in response to infection, stimulates the production of downstream cytokines, such IL-6 and IL-8, and plays a significant role in activating the cytokine cascade." (PMID 28694565, 2017). "We detected a significantly greater TNF-α release by MHS cells after infection with the Δpmt mutant than with the WT or complemented strains and a similar trend was observed in THP-1 cells." (PMID 28801649, 2017).
infection (continued). "In the canarypox prime/protein boost RV144 trial, the elicitation of five-function T cells expressing CD40L, IL-2, IL-4, IFN-γ, and TNF-α or three-function T cells expressing CD40L, IL-2, and IL-4 correlated with a reduced risk of infection." (PMID 29021394, 2017). "LPS-activated NF-κB in combination with LBP, and triggers the pro-inflammatory mediators of APR, such as IL-1β, IL-6 and TNF-α produced by macrophages or blood monocytes at the site of injury or infection." (PMID 28596485, 2017). "Infection of these cells induces an early pro-inflammatory immune response by increased expression of cytokines such as IL-12, TNF-α, and IL-1β." (PMID 29379776, 2017). "Our results on the suppression mechanisms of etanercept and adalimumab in Th17 polarization and cytokine production also provide additional understanding of the adverse effects of TNF-α inhibitors in reactivation of infection." (PMID 27926504, 2017). "Soon after infection (8 hpi), the mRNA levels of the proinflammatory cytokines TNF-α and IL-1β were significantly elevated in the blood of WT and TLR4−/− mice." (PMID 28536433, 2017). "IL-10 knock-out mice infected with T. gondii succumbed within the first 2 week of the infection, with high transcription levels of TNF-α." (PMID 29173277, 2017). "The pro-inflammatory cytokines, tumor necrosis factor-α (TNF-α), interleukin-1β (IL-1β) and IL-6, are the first secreted cytokines in a local infection, such as IE." (PMID 29078765, 2017). "In the self‐resolutive Pcc model, six of 10 peptides tested elicited IFNγ/TNF‐producing CD4 responses at day 6 post‐infection (Fig EV2B)." (PMID 28935714, 2017). "Blood was collected before (day −10) and during infection (day 3) to evaluate anti-TNF-α antibody levels." (PMID 29184553, 2017). "We identified IL-1β as a key cytokine capable of inducing IL-1β, IL-6, TNF-α, and trypsin in mouse lungs and human alveolar A549 cells in the early phase of infection." (PMID 27714503, 2017). "The same was true at day 4 post‐infection (Fig EV4B) indicating that cDC1 are not only important for maintenance of IFNγ+ TNF+ Th1 cells but also for their priming." (PMID 28935714, 2017). "Inflammatory factors, such as TNFα and chemokines including Ccl2, Ccl5, Ccl9 and Cxcl2, were upregulated in response to more than one type of infection, particularly L. m and VSV." (PMID 28088779, 2017). "In response to an infection, cytokines like interleukin (IL)-1, IL-6, and tumor necrosis factor (TNF)α, produced by immune cells, can activate the hypothalamus–pituitary–adrenal (HPA) axis, which results in the secretion of cortisol." (PMID 28674532, 2017). "Participants were asked if anti-TNF/DMARD medication should be temporarily withheld if they experienced different symptoms/infections." (PMID 28526972, 2017). "In a theoretical ancestral setting, ‘at risk' alleles, such as the TNF-α 308A allele, may maintain plasma glucose in the harshest of conditions, allowing cerebral energy load to be maintained in the face of famine, acute stress (such as attack or flight), and infection." (PMID 27555379, 2017). "Physicians who prescribe TNF-α inhibitor drugs must understand the therapeutic implications on patients’ immunity and the potential risks of infection, in order to maximize therapeutic benefits and minimize adverse effects." (PMID 29065914, 2017). "After super-infection, mRNA levels of IL-6, TNFα, CCL3 and CCL5 were substantially increased, especially at 8 h p.i.." (PMID 28195157, 2017). "In the presence of PDLF, TNF-α secretion was significantly decreased (P value < 0.001) and remained minimal even at increasing multiplicity of infection (MOI) of the bacteria." (PMID 28912533, 2017). "CBMO expressed less pro-apoptotic TNFR1, which, after administration of TNF-α or infection with E. coli was internalized to a lesser extent." (PMID 28793310, 2017).
infection (continued). "Evaluation of cells accumulated in the pleural cavity at day 14 post-infection showed higher cell numbers in tmTNF KI mice than in WT mice but TNF KO mice had twofold higher cell numbers compared with WT mice." (PMID 28890718, 2017). "An infection with adenoviruses can induce a tolerant-like state towards TNF, an effect which prevents LPS-induced mortality and liver injury/failure of the affected mice." (PMID 29250561, 2017). "The expression levels of IL-2, IL-4, IL-6 and TNF-α in calcitriol-treated infected mice were significantly lower than the untreated infected mice on 2 days post-infection (p <0.01)." (PMID 28114957, 2017). "Apart from that, IL-17A/F and TNFα can also have pathological effects, which is clearly true in the infection with R. typhi." (PMID 28770333, 2017). "The optimized cut-offs for infection diagnosis for GM-CSF and TNF-α produced higher sensitivities and specificities versus CRP, HS-CRP, and PCT." (PMID 28264059, 2017). "Following tissue injury or infection, the macrophages usually exhibit a pro-inflammatory phenotype and secrete pro-inflammatory mediators, such as TNF-α, IL-1, ΝΟ and ROS, which participate in the activation of various antimicrobial mechanisms." (PMID 28804688, 2017). "The splenic CD11b+ macrophages from mice 0, 1, 3, 5, 7, and 9 days post-infection were obtained to detect the mRNA expression of TNF-α." (PMID 28824565, 2017). "The percentages of T1-type T cells except for CD8+TNF-α+ T cells gradually decreased in HDG from 12 to 24 weeks post-infection." (PMID 28894272, 2017). "M2 markers were repressed whereas the M1 markers IL-6, TNF-α and IL-12 p40 were enhanced when C/EBPβ was knocked down prior to infection, suggesting that C/EBPβ regulates the M1/M2 balance in infected macrophages." (PMID 28558034, 2017). "Circulatory IFN-γ, IL-4, IL-5, IL-6 and TNF-α were increased in WT mice after infection with PcAS (respectively, p = 0.004, 0.004, 0.0081, 0.004 and 0.004)." (PMID 29062028, 2017). "Lung histology confirmed that anti-TNF-α treatment vastly reduced infection-triggered inflammatory infiltrates in HDM allergic animals which was also reflected by the decreased number of PAS+ cells and the low-inflammation score." (PMID 29184554, 2017). "During early infection, all TNF−/− mouse organs showed a marked increase in weight as compared with the other groups, with the exception of lung and spleen of etanercept-treated mice." (PMID 29184553, 2017). "The cytokine cascade events following B. pseudomallei infection has been studied in several animal models and show an up regulated mRNA expression of inflammatory cytokines such as IL6, IL12, IL10, IFNγ, TNFα and IL1β within 72 hours of infection." (PMID 28628607, 2017). "Both H-2b- and H-2d-restricted CD8 T cell epitopes from D2B6F1 mice exhibited a greater frequency of IFN-γ and IFN-γ/TNF co-producing CD8 T cells than BCF1 mice following either Arm or Cl-13 infection." (PMID 28715493, 2017). "For this, the cells were treated with TNF siRNA prior to infection with B. abortus (MOI: 100) which was followed by staining with Apopxin and 7-ADD indicators and finally evaluated at 48 h pi by flow cytometry." (PMID 29062811, 2017). "The infection also activated many signaling pathways of effector molecules, including the TNF signaling pathway (ko04668), cytokine-cytokine receptor interaction (ko04060), the chemokine signaling pathway (ko04062) and the phagosome pathway (ko04145)." (PMID 28899359, 2017). "Interleukin-8 is a proinflammatory chemokine that is released in response to IL-1 or TNF-α as a result of environmental stressors such as infection, hypoxia and chemotherapy, and can act as a neutrophil chemoattractant." (PMID 29181334, 2017). "Twenty-four hours post infection, cells were stimulated with LPS and the levels of TNFα and IL-6 were measured." (PMID 28118607, 2017).
infection (continued). "Our results showed the intestinal fluids of AKT-blocked mice produced significantly more IL-12 p40, IFN-γ, TNF-α, and IL-6 during the early stage of infection (5 dpi) compared with infected WT mice." (PMID 28979269, 2017). "Compared to the BALB/c strain, IL-1RI−/− mice had significantly reduced expression of KC, TNFα, and MCP-1 that was associated with increased lung fungal burden at day 7 after infection." (PMID 29403476, 2017). "Flow cytometry analysis found that not only is the CD163+ population more prone to infection with Leishmania parasites but produces more IL-4 and TNF-α than CD163- macrophages." (PMID 28355218, 2017). "Upon infection, macrophages in the lung are activated in response to inflammatory cytokines (TNF-α, IFN-γ) and/or the presence of bacteria." (PMID 28817561, 2017). "In contrast, TNF-α levels in the control/A(H1N1)pdm09 group increased to 63.7 pg/mL at 3 days post-infection, and peaked to 110.7 pg/mL by 7 days post-infection (p = 0.12)." (PMID 28831046, 2017). "We tested the efficacy of treatment with the antibiotics ampicillin and ciprofloxacin in mice that had been rendered immunodeficient prior to the commencement of the infection by in vivo neutralization of TNFα." (PMID 28087648, 2017). "At the same time, the production of the M1 markers IL12p40, TNF-α and IL-6 during infection, was augmented by knockdown of C/ebpbeta." (PMID 28558034, 2017). "In spite of this anti-inflammatory scenario, the secretion of TNF-α by Calu-6 cells was indeed increased by the infection with Mtb strains that was dependent on the ingested bacilli." (PMID 28852268, 2017). "We show that infection of macrophage with B. abortus induces marked expression and secretion of TNF which subsequently binds to TNF receptor 1 (TNFR-1) and activates a downstream signaling cascade of the innate immunity." (PMID 29062811, 2017). "To shed light on the mechanism by which TNF fuels astrocyte infection by T. cruzi, we analyzed TNFR1 expression on these glial cells." (PMID 28877735, 2017). "Next, we confirmed that the T. gondii ESA preparations induced TNF-α production in mouse splenocytes or peritoneal macrophages, similar to tachyzoites infection." (PMID 28000706, 2016). "At the same time to understand any modulation of NF-κB signal transduction pathway by the different pathotypes, the cells were co-stimulated with TNF-α after the induction of p65 phosphorylation by the infection." (PMID 27774437, 2016). "For both R and S infections, cells producing TNF-α co-localized with Mabs-containing macrophages, either isolated or within granulomas." (PMID 27806130, 2016). "Remarkably, co-stimulation with TNF-α after 0.5, 1, 2, and 4 h of infection by EAEC, induced levels of p65 phosphorylation very similar to those of cells infected without co-stimulation." (PMID 27774437, 2016). "The relative IL-10 and TNF-α mRNA expression levels produced by the DCs were significantly up-regulated 24 h post-infection with the H9N2 virus." (PMID 27826541, 2016). "Human MAIT cells produce proinflammatory cytokines, e.g., IFN-γ and TNF in response to infection with Mycobacterium smegmatis, Escherichia coli, Salmonella enterica, or Staphylococcus aureus." (PMID 27774092, 2016). "Actually, patients with CL due to L. braziliensis produce high amounts of IFN-γ and TNF, but despite an environment adverse to leishmania proliferation, the infection progresses to disease." (PMID 26840253, 2016). "To confirme the modulation of RelAp43 pathway by the matrix protein of Tha virus, we quantified the transcription of TNF in the brain of mice during the ultimate phase of infection (at the humane endpoint) with Tha and Th4M viruses." (PMID 28000711, 2016). "With a same infective dose, Bp would induce higher TNF-α release and apoptosis levels compared to Bt, especially at the late infection phase." (PMID 27894256, 2016).
infection (continued). "Free alveolar space was already reduced in M-TNF KO and TNF KO 3-weekspost-infection, then similarly in M-TNFR1 KO and TNFR1 KO mice at4–5 weeks, while WT mice remained stable." (PMID 26931771, 2016). "As a pleiotropic cytokine, TNF-α plays a key role in inflammation induced by infection or tissue injury, which can further trigger necroptosis by activating necroptotic markers RIP1 and RIP313." (PMID 27580936, 2016). "Within the infection groups, C57 mice exhibited less serum TNF-α levels than those of diabetic mice (STZ-C57, TH, db/db mice versus C57 mice: P < 0.01)." (PMID 27995146, 2016). "Next, we analyzed the level of proinflammatory cytokines (TNF, IL-6) and nitric oxide (NO), the key components in Leishmania control, in BMDCs cell supernatants 24h post infection." (PMID 27580076, 2016). "The other inhibitors of the infection are macrophages (producing IFNs, TNF-α, and IL-6), and lymphocytes that are instrumental in active immune surveillance by producing IFN-γ." (PMID 27582741, 2016). "The mean level of TNF-α at 24 h post-infection was also higher for H7N9-HU (458-fold) than that of H7N9-CK (224-fold), almost reaching statistical significance (P = 0.068)." (PMID 26975414, 2016). "We were able to demonstrate that both CD4+ and CD8+ influenza virus-reactive T cells accumulate in the lungs of infected pigs from day 4 p.i. onwards, produce mainly IFN-γ and/or TNF-α, and form cross-reactive memory at the site of infection." (PMID 27512056, 2016). "In the acute infection model, IL-6 mRNA over-expression by both SM- and OM-HPBCs infected with S. aureus, as well as the weak responses in IL-1β and TNF-α mRNA expressions, were already observed during S. aureus and mesenchymal stem cell interaction." (PMID 27446812, 2016). "The role of TNF-α in host resistance to infection by L. major has beenknown since the 1990s when its protective effect was suspected to relate to its abilityto activate macrophage leishmanicidal activity (Liew etal." (PMID 27759762, 2016). "Co-expression of IFN-γ/TNF-α/TGF-β was significantly affected by METH in the CD4 T cell subpopulation that was very dramatic at the last time point (day 56) of infection." (PMID 27760221, 2016). "We used anti-IL-17A or IL-17F antibody (500 μg/mouse, 20 mg/kg) or anti-TNFα antibody (250 μg/mouse, 10 mg/kg) or the respective isotype control IgG antibodies, administered weekly, starting 1 day before infection." (PMID 27853279, 2016). "Based upon our RT-PCR analysis of IL-6, IL-10 and TNFα in macrophages infected with legS2 mutants, we can conclude that infection with L. pneumophila legS2 dampens the mRNA expression of cytokines in infected cells." (PMID 26741365, 2016). "M. mass led to an increase in TNF-α level compared to uninfected samples 3 days post-infection (P<0.05)." (PMID 27489303, 2016). "In contrast, reduced chlamydial shedding following challenge infection in vaccinated mice, has been attributed to the co-expression of TNF-α and IFN-γ." (PMID 27219467, 2016). "The infection resulted in a strong increase of the mRNA expression of TNF-α in the hippocampus and cortex of infected WT mice (29.7 ± 6.6-fold and 113 ± 33-fold induction of expression)." (PMID 27057100, 2016). "Infected WT mice had increased TNF-α and IL-6 throughout the duration of infection, while the inflammatory cytokine response in β6 KO mice was less robust." (PMID 27505057, 2016). "Infection of eWT or eK201R triggered macrophages to secrete cytokines including IL-18, IL-1β and TNF-α." (PMID 26943369, 2016). "TNFα is a major pro-inflammatory cytokine first identified as a serum-derived factor upon infection." (PMID 27306736, 2016). "We also measured the production of pro-inflammatory cytokines TNF-alpha, IL-6 and KC at 2 h and 6 h post-infection both in the peritoneal washes and in blood samples." (PMID 27655040, 2016).